TNF (tumor necrosis factor)
Diseases named in the same sentence as TNF in open-access papers (continued):
Sharing a sentence is not in itself a finding about the gene and the disease.
anthrax (8 papers, 2008 to 2024). "Indeed, our finding that the IECs are the key cell target of LT + TNF is reminiscent of the clinical evidence that intestinal damage is one of the leading causes of lethality in anthrax patients." (PMID 37855658, 2024). "Thus, preventing TNF-induced apoptosis and necroptosis in combination with controlling bacterial propagation might be an effective prevention of anthrax-caused death." (PMID 37855658, 2024). "Genetic deletion of p38α in IECs mimicked LT treatment in sensitizing small intestines to TNF-induced damage and mouse death, supporting the role of p38α inactivation in the pathology of anthrax." (PMID 37855658, 2024). "During anthrax infection, B. anthracis has been known to reach 107-108 organisms per milliliter of blood and induce high amount of cytokines such as TNF-α, IL-6, and IL-1β in primary macrophages and an experimental animal model." (PMID 25472474, 2014). "In pulmonary anthrax, the unlocking effect of cSN50 peptide on suppressed innate immunity mediators (TNFα, IL6, and MCP-1) is consistent with bimodal regulation of genome-wide response by this nuclear transport modifier." (PMID 22291977, 2012). "The secretion of TNFα from monocytes stimulated with PGN is consistent with a model of anthrax as a septic disease." (PMID 19002259, 2008). "As intestinal damage is one of the leading causes of lethality in anthrax patients, the IEC damage caused by LT + TNF would most likely be a mechanism underneath this clinical manifestation and could be a target for interventions." (PMID 37855658, 2024). "Our results suggest that B. anthracis DNA may contribute to anthrax pathogenesis by enhancing LT activity via TLR9-mediated TNF-α production." (PMID 25472474, 2014). "In our study, at 24 h post-infection with B. anthracis spores, the amount of BAG circulating in the blood was <0.89 μg/ml, but it may increase as anthrax infection develops in mice, resulting in TNF-α production." (PMID 25472474, 2014). "In addition, detection of BAG in the sera of anthrax spore–infected mice is consistent with a possible role for BAG-induced TNF-α in the lethality in mice." (PMID 25472474, 2014). "Therefore, TNF-α secretion by BAG as well as by other components of B. anthracis could contribute to pathogenesis of anthrax." (PMID 25472474, 2014). "This is an experimental study aimed to compare the effect of EEP 200 mg on the level of TNF-α and MDA between the rat model of inhalation and cutaneous anthrax after 14 days." (PMID 35047724, 2022). "EEP has a better effect on reducing TNF-α and MDA in cutaneous anthrax animal models compared to the inhalation anthrax animal model." (PMID 35047724, 2022). "This study aimed to compare the effects of ethanolic extract of propolis (EEP) on TNF-α and MDA between the inhalation and cutaneous anthrax animal model." (PMID 35047724, 2022). "Based on these observations, we postulated that BAG and other virulence factors during anthrax infection are recognized by TLR9 and their corresponding receptors, which induce TNF-α production via MAPK and NF-кB signaling pathways." (PMID 25472474, 2014). "The current study demonstrates that BAG during anthrax infection is recognized by TLR9 and this recognition stimulates TNF-α production via MAPK and NF-κB pathways in mouse macrophages." (PMID 25472474, 2014). "Elevated transcription of TNF-α, IL-1α, IL-1β, IL-4, IL-6, CCL5, CXCL2 and KC have been observed in both murine anthrax challenge models and in vitro macrophages and monocytic cell lines exposed to anthrax antigens." (PMID 26075052, 2015). "This large cellular TNF-α response to toxigenic spores compared to a lower one in the nontoxigenic spore-challenge is an interesting observation, suggesting that the issue of cytokine suppression during anthrax is not straightforward." (PMID 19014542, 2008).
anthrax (continued). "Thus, cutaneous anthrax induces a broad T cell memory response characterized not only by the presence of Th1 cytokines IFNγ and TNFα, but also Th2 (IL-5 and IL-13), Th17 (IL-17/IL-22), Th22 (IL-22) and Th9 (IL-9) cytokines and a potentially regulatory IL-10 response." (PMID 26075052, 2015).
aseptic meningitis (8 papers, 2008 to 2024). Inflammation of the membranes surrounding the brain and spinal cord without a bacterial pathogen. "This case report describes aseptic meningitis as a previously unreported complication of etanercept therapy, and serves as a reminder of the rare but potentially life-threatening risk of serious infections in patients taking anti-TNF therapy for a variety of conditions." (PMID 19046446, 2008). "A potential pathophysiologic mechanism highlights the role of IL-1, IL-6 and tumor necrosis factor-alpha (TNF-α) in the pathogenesis of aseptic meningitis in FMF and CINCA syndrome." (PMID 32765981, 2020). "Several case reports have described aseptic meningitis that has resulted from medication use like anti-tumor necrosis factor alpha (anti-TNF α) agents as Infliximab or Adalimumab and even from csDMARDs like Methotrexate, Salazopyrine, or Leflunomide." (PMID 32471260, 2020). "We will discuss the emerging role of proinflammatory cytokines, such as interleukin 1 (IL-1), interleukin 6 (IL-6) and tumor necrosis factor-alpha (TNF-α), in the pathogenesis of aseptic meningitis in ADs, and will explore recent treatment developments, such as the use of biological agents." (PMID 32765981, 2020). "Cerebral vascular changes and leukocyte-endothelium interactions were surveyed by intravital videomicroscopy utilizing a novel in vivo model of localized aseptic meningitis when TNFα was introduced intracerebrally in wild-type (PARP+/+) and PARP-deficient (PARP−/−) mice." (PMID 27677851, 2016).
cholangitis (8 papers, 2015 to 2025). An acute or chronic inflammatory process affecting the biliary tract. "Meanwhile, Kulkarni et al16 found that PSC-IBD patients receiving anti-TNFα therapy had a more than 3-fold odds of developing bacterial cholangitis (OR 3.45, 95% CI, 1.54-7.76), with 50% of patients developing cholangitis within 36 months of starting therapy." (PMID 41141435, 2025). "In patients with a previous inflammatory condition such as cholangitis or other infections, we observed that TNFα, CRP and leukocytes were elevated prior to ERCP, but remained stable 4 hours after the procedure." (PMID 27642079, 2016). "In addition, a study reported that antigen-specific CD8+ T cells, which contact with hepatocytes, can control bile acid metabolism in a murine model of cholangitis, and that these effects partly depend on TNF and IFN-γ." (PMID 35514982, 2022). "It has been previously shown that expression of IL-8 in human biliary epithelial cells is stimulated by proinflammatory cytokines IL-1β and TNF-α, and lipopolysaccharide produced by gram negative bacteria, which are commonly causative microbes underlying BA associated cholangitis." (PMID 34207442, 2021). "None of the four anti-TNF treated patients developed infectious complications; in one UC patient infliximab treatment was stopped prophylactically because of recurrent episodes of cholangitis most likely caused by stenosis of the biliary-enteric anastomosis." (PMID 26288187, 2015).
choroidal neovascularization (8 papers, 2010 to 2023). An eye disorder described by the growth of new blood vessels that originate from the choroid through a break in the Bruch membrane into the sub–retinal pigment epithelium (sub-RPE) or subretinal space. "Increased TNF-α is also associated with monocyte activation, as patients with higher prevalence of choroidal neovascularization demonstrated high levels of monocyte TNF-α." (PMID 36926522, 2023). "–50 Similarly, inflammation as indicated by macrophage infiltration is also observed in the laser-induced choroidal neovascularization (CNV), a well-characterized model for wet AMD51 and anti-TNF-α treatment reduced lesion area and leakage of CNV." (PMID 35579886, 2022). "We investigated the effects of lacking TNFα on the development and regression of Argon‐laser‐induced choroidal neovascularization (CNV) in mice." (PMID 36127870, 2022). "Interestingly, intravitreal injection of decorin in a choroidal neovascularization (CNV) mouse model was able to suppress TGF-β, VEGF, and TNFα upregulation." (PMID 34947953, 2021).
chronic endometritis (8 papers, 2016 to 2025). A non-granulomatous or granulomatous chronic inflammation of the endometrium. "Previous studies revealed that inflammatory factors IL-6 and TNF-α were significantly increased in the menstrual blood of women with chronic endometritis." (PMID 37446399, 2023). "Nonetheless, in another study, IL-6, IL-1β and TNF-α levels were investigated in menstrual effluents of women with chronic endometritis." (PMID 27152525, 2016). "Chronic endometritis induces the release of superoxide radicals and tumor necrosis factor from inflammatory cells, which subsequently stimulate the proliferation of mesenchymal cells capable of undergoing metaplasia and differentiating into chondroblasts or osteoblasts." (PMID 40861427, 2025). "For this aim, expression of mRNAs for Toll-like Receptor 2 and 4 (TLR 2/4), interleukin 1β (IL-1β), interleukin 6 (IL-6) and tumor necrosis factor α (TNF) was examined in control mares versus either mares suffering from chronic endometritis (ChE) or subacute suppurative endometritis (SSE)." (PMID 27152525, 2016). "Furthermore, a logistic regression analysis provided evidence that the IL-6/TNF-α-based model, excluding IL-1β, is a significant predictor of chronic endometritis, which is in accordance with the present results." (PMID 27152525, 2016). "Our analysis showed statistically significant lower levels of uterine cytokines TNF-α (p = 0.001) and IL-1beta (p = 0.000) in the KIR AA genotype group as compared to KIR AB and BB among study participants with chronic endometritis." (PMID 37835791, 2023). "The statistical analysis showed significant correlations between chronic endometritis and the levels of TNF-α, IL-1β, and LIF cytokines (p < 0.0001), and also between chronic endometritis and hysteroscopic findings (p < 0.0001)." (PMID 37835791, 2023). "The results of the immunofluorescence assay also illustrated a significant presence of TNF-α and CD38 signals in the endometrial tissues of the chronic endometritis group compared to those in the healthy group and the control group." (PMID 34234149, 2021). "The Wilcoxon–Mann–Whitney test showed statistically significant lower median concentration levels of uterine cytokines TNF-α (p = 0.001) and IL-1 β (p = 0.000) in the KIR AA genotype group as compared to KIR AB and BB, among study participants with chronic endometritis." (PMID 37835791, 2023). "As regards the uterine cytokines, we found higher levels of IL-1β and TNF-α, and lower levels of LIF in patients with chronic endometritis, regardless of the KIR genotype." (PMID 37835791, 2023).
colon adenoma (8 papers, 2013 to 2025). An adenoma that arises from the colon. "The present study explored serum adiponectin, leptin, IGF-1, and TNF-α association with colon adenoma." (PMID 29593647, 2018). "Our study is also the first to examine haplotype-tagging SNPs as well as circulating levels of IL-6 and TNF-α and risk of colon adenomas in Caucasians and African Americans separately." (PMID 24235998, 2013). "We sought to determine whether circulating levels of IL-6 and TNF-α, or genetic polymorphisms in IL-6and TNF-α were associated with colon adenoma and if so, whether that association differed by race." (PMID 24235998, 2013). "We investigated the associations between circulating levels and genetic variants of IL-6 and TNF-α and colon adenomas in a case-control study including 894 Caucasians and 557 African Americans who underwent routine colonoscopy at University Hospitals Case Medical Center, Cleveland, Ohio." (PMID 24235998, 2013). "Specifically in this study we sought to determine whether inflammation, as measured by inflammatory cytokines IL-6 and TNF-α, exhibited similar associations with colon adenomas in both Caucasians and African Americans in our study." (PMID 24235998, 2013). "We also evaluated the association of SNPs in the IL6 and TNF-α genes and colon adenomas." (PMID 24235998, 2013). "Herein, we observed that AcSDKP inhibited TNF-α-induced inflammatory cytokines and chemokines expression at mRNA levels in Caco-2 colonic adenoma cells, and the inhibitory effect was dependent on the concentration of AcSDKP." (PMID 32435194, 2020). "IFN-γ, TNF-α, and IL-2 enhance cytotoxic and apoptotic effects in response to colon adenomas." (PMID 38343544, 2024). "Our results do not support pre-diagnostic levels of IL-6, TNF-α or their genetic variants as significant risk factors for the development of colon adenoma." (PMID 24235998, 2013). "MIBE mediators, such as TNF-α, 4-HNE and ROS, have been detected in human colon adenomas, although such associations do not prove causation and many questions remain unanswered." (PMID 33969420, 2021). "The differences were statistically significant (P<0.05), and the expression levels of IE1–72, TLR4 and TNF-α in the colon adenoma were evidently higher than those in normal tissue (P<0.05)." (PMID 25435993, 2015).
Coma (8 papers, 2009 to 2022). The complete absence of wakefulness and consciousness, which is evident through a lack of response to any form of external stimuli. "When somnolence is produced in excess, IL-6 and tumor necrosis factor α (TNF-α) are elevated, with a subsequent rise in the number of monocytes and neutorphils." (PMID 22084580, 2009).
complication (8 papers, 2010 to 2025). Any disease or disorder that occurs during the course of, or because of, another disease, treatment, or procedure. "The observed induction of IL-6, IL-1β and TNFα in hypercoagulable diabetic mice is consistent with these observations and with the perception of diabetic vascular complications as inflammation-driven diseases." (PMID 35631132, 2022). "The observed induction of IL-6 and TNFα in glucose stressed macrophages is entirely congruent with these observations and with the perception of diabetic vascular complications as inflammation driven diseases." (PMID 30271984, 2018). "The most common side effects in the TNF inhibitors group were infection and skin complications." (PMID 39480594, 2024). "Likewise, IL-6 and TNF-α, in addition to a number of other cytokines, are excessively active in patients who have developed HCT-associated endothelial complications." (PMID 36733348, 2022). "The EURODIAB Prospective Complication Study hypothesized that a Z-score composed by C-reactive protein (CRP), Tumor Necrosis Factor-α (TNF-α), and interleukin-6 (IL-6) could be associated with the presence of vascular complications in diabetic patients." (PMID 27376090, 2016).
Crohn's colitis (8 papers, 2015 to 2025). Crohn's disease affecting the colon. "We present a case of a teenage patient with Niemann-Pick disease type C and Crohn colitis, who sustained clinical remission only after escalating to dual biologic therapy (anti-tumor necrosis factor alpha [infliximab] and anti-interleukin-12/anti-interleukin-23 [ustekinumab])." (PMID 37168644, 2022). "Furthermore, in bioinformatics analysis, mucosal Th1 cytokine of TNF, showed a double-edged role in UC when compared to the Th1-mediated disease of Crohn's colitis." (PMID 29228739, 2017). "Although they mediate similar therapeutic effects in RA, anti-TNF antibodies but not ETN are effective in other chronic inflammatory disease such as Crohn’s colitis." (PMID 28824652, 2017).
Ehrlich tumor (8 papers, 2015 to 2024). "Regarding solid Ehrlich tumors, it was observed that treatment with CE induced a significant increase in TNF-α levels in the tumor." (PMID 39861087, 2024). "The serum level of the cytokines IL-1β and TNF-α was determined in mice injected with the solid Ehrlich tumor." (PMID 38774541, 2024). "Although TNFα induces hemorrhagic necrosis in certain solid tumors, intraperitoneal tumors, such as Ehrlich tumor, are resistant to its cytotoxic effect." (PMID 26347589, 2015). "In contrast, using the methanolic extract of Arthrocnemum machrostachyum for the treatment of solid Ehrlich tumors, Sharawi (2020) observed that TNF-α levels were reduced after treatment, suggesting that such a reduction is important to prevent tumor cell survival." (PMID 39861087, 2024). "Our results indicate that treatments with CE and EAF, both at a 10% concentration, were able to regulate the metabolic imbalance caused by the tumor and inhibit the growth of ascitic and solid Ehrlich tumors by inducing apoptosis and modulating mast cells and the cytokines IL-6 and TNF-α." (PMID 39861087, 2024). "In agreement with previous studies using different cancer cachexia models, Ehrlich tumor development presented characteristics of pro-inflammatory scenario, as demonstrated by significant (P <.05) elevated TNF-α and IL-6 in plasma of tumor-bearing mice compared to the control group." (PMID 35847939, 2022). "The results show that the Ehrlich tumor did not induce an increase in serum levels of IL-1β and TNF-α compared to the control group." (PMID 38774541, 2024). "The serum level of IL-1β, but not TNF-α, increased in mice with the solid Ehrlich tumor and treated with chloroquine." (PMID 38774541, 2024). "Mice injected with the solid Ehrlich tumor and infected with Plasmodium berghei presented an elevation of serum level of IL-1β, but not TNF-α." (PMID 38774541, 2024). "Mice with the solid Ehrlich tumor that was treated with chloroquine and healed from malaria infection presented an elevation of serum level of IL-1β, but not TNF-α, compared to the control." (PMID 38774541, 2024). "Our results showed that ACS-AZ modulates the immune system by increasing TNF-α levels to potentiate antitumor immunity, without inducing significant toxicity on mice bearing Ehrlich tumor." (PMID 36324671, 2022).
enthesitis-related arthritis (8 papers, 2014 to 2025). "Compared to those derived from HCs, neutrophils derived from patients with oligoarticular-JIA, polyarticular-JIA and enthesitis-related arthritis were more prone to generate NETs spontaneously and in response to TNF-α or PMA in vitro." (PMID 39185410, 2024). "The panniculitis demonstrated a sustained response when a tumor necrosis factor alpha inhibitor was used for enthesitis-related arthritis." (PMID 37697374, 2023). "While studies mention that adalimumab is superior to etanercept for biologic-naive juvenile enthesitis-related arthritis (ERA), our choice of anti-TNF inhibitor was mainly due to availability at the time of treatment." (PMID 40406765, 2025).
epithelial dysplasia (8 papers, 2009 to 2025). "Here, we report that HFD modified the final body weight and the weight gain, decreased the expression of the androgen receptor and increased prostatic inflammation via TNF-α produced damage prostatic like intraepithelial neoplasia." (PMID 33737530, 2021). "Moreover, it was reported that the expression of TNF-α is significantly increased in lesions exhibiting epithelial dysplasia." (PMID 32245251, 2020). "Indeed, about 70% of the mice with gastric lesions had intraepithelial neoplasia, and the overgrowth of Lactobacillus murinus ASF361 correlated with enhanced gastric inflammation and the expression of cancer-related factors, such as TNF-α, Ptger4, and TGF-β." (PMID 41304185, 2025). "We presume that in intraepithelial neoplasia, the body compensatorily up-regulates the expression of IGFBP-5, which activates the caspase-8 signal transduction pathway, increases the structure sensitivity to TNF-α, induces the internal apoptosis pathway, and delays tumor advancement." (PMID 19476635, 2009).